TLR1 (toll like receptor 1)
Diseases named in the same sentence as TLR1 in open-access papers (continued):
Sharing a sentence is not in itself a finding about the gene and the disease.
Bartonella infection (1 paper, 2025). "Notably, four key sites influencing Bartonella infection susceptibility were identified, with two on TLR1 and one each on TLR4 and TLR10." (PMID 40678527, 2025). "Previous studies have revealed that specific sites on TLR1, TLR2, and TLR5 genes were significantly associated with the risk of Bartonella infection." (PMID 40678527, 2025). "In this study, we analyzed the polymorphisms in six cell surface TLR genes (TLR1, TLR2, TLR4, TLR5, TLR6, and TLR10) in striped hamsters, aiming to determine their association with Bartonella infections and ectoparasite parasitism, including fleas and gamasid mites." (PMID 40678527, 2025). "The genotypes at positions 1331 of TLR1, 36 of TLR4, and 2187 of TLR6 significantly affected Bartonella infection, with MDGs of 3.08, 2.33, and 3.22, respectively." (PMID 40678527, 2025).
basal cell carcinoma (1 paper, 2022). A carcinoma involving the basal cells. "Genes in the low-expression cohorts of CD14, CYBB, NOD2, and TLR1 were all highly enriched in olfactory transduction, linoleic acid metabolism, and basal cell carcinoma." (PMID 36193326, 2022).
bipolar disorder (1 paper, 2016). A disorder of the brain that causes unusual shifts in mood, energy, activity levels and the ability to carry out day-to-day tasks. "TLR1 was proposed to be among the factors that affect the clinical phenotype of schizophrenia and bipolar disorder." (PMID 26415953, 2016).
Chagas disease (1 paper, 2018). A parasitic infection caused by Trypanosoma cruzi. "On the other hand, patients with different clinical manifestations of Chagas disease showed similar mRNA expression levels of TLR1, TLR3, TLR4, TLR5, TLR6, TLR7 and TLR9." (PMID 30044791, 2018). "Patients with different clinical manifestations of Chagas disease showed similar expression of TLR1, TLR3, TLR4, TLR5, TLR6, TLR7 and TLR9 mRNA." (PMID 30044791, 2018).
childhood asthma (1 paper, 2015). "In line, an earlier study investigating several SNPs within TLR-1 and −6 (P249S) showed that they are associated with an increased risk for childhood asthma." (PMID 26157469, 2015).
chorioamnionitis (1 paper, 2020). A morphologic finding indicating inflammation of the fetal sac membranes. "The increased expression of TLR1 at the gene level in preterm fetal membranes with histological chorioamnionitis has been described, as have increases in TLR1, TLR2, TLR4, and TLR6 in chorioamniotic fetal membranes." (PMID 32625109, 2020).
convulsion (1 paper, 2021). A rapid and repeated body muscle contract that results in an uncontrolled shaking of the body. "The three crucial changes that induce convulsions include an increase in HMBP 1, interaction with toll-like receptor-1 (TLR1), interleukin-β (IL-β) interaction with its receptors, and increased tumor growth factor-β (TGF-β) signaling." (PMID 33987052, 2021).
dental caries (1 paper, 2024). The decay of a tooth, in which it becomes softened, discolored, and/or porous. "In future gene association studies of dental caries, other genes involved in Toll-like receptor-mediated pathogen recognition and/or regulation, such as TLR1 (Toll-like receptor 1 gene), TLR6 (Toll-like receptor 6 gene), and MD-2 (myeloid differentiation-2 gene), should also be considered." (PMID 39000094, 2024).
diffuse cutaneous Leishmaniasis (1 paper, 2025). A form of LEISHMANIASIS, CUTANEOUS caused by Leishmania aethiopica in Ethiopia and Kenya, L. pifanoi in Venezuela, L. braziliensis in South America, and L. mexicana in Central America. "It has been reported that patients with diffuse cutaneous leishmaniasis exhibited a reduced number of NK cells, lower levels of cytokines, such as IFN-γ, and diminished TLR expression, as is the case of TLR1, TLR2, and TLR6." (PMID 39963187, 2025).
Dysmenorrhea (1 paper, 2017). Pain during menstruation that interferes with daily activities. "After statistical analysis confirmed that: The gene expression of TLRS (TLRS = TLR1 + TLR2 + TLR3 + TLR4 + TLR5 + TLR6 + TLR7 + TLR8 + TLR9) in severe and moderate dysmenorrhea group was significantly higher than that in minimal dysmenorrhea group in EU and EC (P < 0.05 or P < 0.01)." (PMID 28779087, 2017).
endometritis (1 paper, 2014). An acute or chronic, usually bacterial infectious process affecting the endometrium. "The ability of endometrial cells to detect and respond to bacterial lipopeptides via TLR2/TLR1 and TLR2/TLR6 is probably important for the onset and persistence of endometritis in cattle." (PMID 24437488, 2014).
Fasciola hepatica infection (1 paper, 2022). "This was also similar to a previous report that Fasciola hepatica infection can comprehensively suppress Toll-like receptor expression in ovine PBMCs at the acute infection stage, leading to downregulation of the transcription level of TLR1/5/67/10 in ovine PBMC." (PMID 35739856, 2022).
gastrointestinal infection (1 paper, 2021). "Besides, based on a previous study, lack of TLR1 during gastrointestinal infection end up in the activation of chronic immunity, which might confirm the fact that TLR1 and its signaling pathway can inhibit inflammation in IBD patients." (PMID 33902702, 2021).
gout (1 paper, 2012). A condition characterized by painful swelling of the joints, which is caused by deposition of urate crystals. "We stimulated PBMCs of patients with gout and of healthy donors with either the TLR2/6 ligand FSL-1 or TLR1/2 ligand Pam3Cys." (PMID 22762240, 2012). "PBMCs from 18 patients with primary gout and 12 healthy donors were exposed to MSU crystals in the presence or absence of saturated fatty acid C18:0 (free fatty acid, TLR2 ligand), palmitoyl-3-cystein (Pam3Cys, TLR1/2 ligand) and fibroblast stimulating factor-1 (FSL-1, TLR 2/6 ligand)." (PMID 22762240, 2012).
Granuloma (1 paper, 2024). A compact, organized collection of mature mononuclear phagocytes, which may be but is not necessarily accompanied by accessory features such as necrosis. "One of the studies, reported adverse effects, including fever, chronic inflammation, and granuloma in the use of TLR1/2, TLR9, and TLR8 agonists combination administered intramuscularly in swine." (PMID 39355141, 2024). "Adverse effects, including fever, chronic inflammation, and granuloma, were reported using a combination of TLR1/2, TLR9, and TLR8 agonists in swine." (PMID 39355141, 2024).
head and neck squamous cell carcinoma (1 paper, 2022). A squamous cell carcinoma that arises from any of the following anatomic sites: lip and oral cavity, nasal cavity, paranasal sinuses, pharynx, larynx, and salivary glands. "TLR-9, TLR-5, TLR-4, TLR-3, TLR-2 and TLR-1 are linked to some clinical parameters of patients afflicted with head and neck squamous cell carcinoma (HNSCC)." (PMID 36224753, 2022).
heart failure (1 paper, 2025). Inability of the heart to pump blood at an adequate rate to meet tissue metabolic requirements. "Although TLR1 has not been directly linked to cardiovascular disease (CVD), one study demonstrated that TLR2 activates cardiac remodeling in a TLR1-dependent manner in a heart failure mouse model." (PMID 39828779, 2025).
helminth infections (1 paper, 2025). "Although the regulation of CRAMP in macrophages via activation of TLR1/2 has been well studied for bacterial infections (e.g., Mycobacterium tuberculosis) in humans, it remains poorly investigated in mice, particularly for helminth infections." (PMID 40266093, 2025).
Hodgkins lymphoma (1 paper, 2018). A heterogeneous group of malignant lymphoid neoplasms of B-cell origin characterized histologically by the presence of Hodgkin and Reed-Sternberg (HRS) cells in the vast majority of cases. "miR-200a-3p is associated with Hodgkin lymphoma, and potentially in regulating pathogen recognition in miiuy croaker through TLR1 targeting, an essential component of TLRs in bacterial pathogen defense." (PMID 30458711, 2018).
hypothyroidism (1 paper, 2022). Abnormally low levels of thyroid hormone. "As an example, the most significant pathway detected by PANTHER is a toll-like receptor signaling pathway for co-cluster 111 comprised of hypothyroidism/myxedema and levothyroxine sodium medication, and genes TLR1, TLR6, and TLR10 in the cells—EBV-transformed lymphocytes tissue." (PMID 35987940, 2022).
inflammatory bone diseases (1 paper, 2025). "In addition, SCSP modulates inflammatory cascades by attenuating IL-17 signaling, Toll-like receptor pathways, and key genes implicated in inflammatory bone diseases, such as Ccl2, Il17re, Fosl1, Mmp13, Ccl5, Tlr1, Il12b, and Atp6v1b1." (PMID 40926992, 2025).
keloid (1 paper, 2024). An irregularly shaped, elevated mark on the skin caused by deposits of excessive amounts of collagen during wound healing. "Among the genes induced in keloids are Tlr1, Tlr2, Tlr6, and Acod1, commonly up-regulated by bacteria." (PMID 39081787, 2024).
leishmaniasis (1 paper, 2021). Infectious disease that is transmitted through the bite of hematophagous female phlebotomine sand flies. "In diffuse cutaneous (DCL) leishmaniasis that is characterized by uncontrolled parasite dissemination and poor production of IFN-γ patients showed reduced NK cell numbers that down-regulated TLR2, TLR1 and TLR6 expression as well as reduced cytokine production, as compared to CL patients." (PMID 34691019, 2021).
liver disease (1 paper, 2017). "The increased TLR1/2, TLR2/6, and TLR4 expression may lead to exaggerated immune responses triggered by bacterial infection in HBV-related ACLF patients, and thus promotes the deterioration of liver disease." (PMID 29218046, 2017).
mantle cell lymphoma (1 paper, 2014). Mantle cell lymphoma is a rare form of malignant non-Hodgkin lymphoma affecting B lymphocytes in the lymph nodes in a region called the ``mantle zone''. "In mantle cell lymphoma (MCL), TLR1, TLR4, TLR7, TLR9 and TLR10 exhibit significant mRNA levels, whereas TLR2, TLR3, TLR5 and TLR8 are negative." (PMID 25112836, 2014).
meningitis (1 paper, 2022). A disorder characterized by acute inflammation of the meninges of the brain and/or spinal cord. "However, when we subcategorized LNB patients by clinical presentation, patients with meningoradiculoneuritis had a significantly higher frequency of TLR1–1805GG SNP compared to patients with PFP/meningitis (68% vs. 40%; odds ratio 3.1; p = 0.04)." (PMID 35318928, 2022).
mycobacterial infection (1 paper, 2012). "It would therefore be expected that individuals homozygous for TLR1 602S would have increased susceptibility to mycobacterial infection." (PMID 22529866, 2012). "However, a number of functionally deficient polymorphisms in TLR1 and TLR4 have been found to confer protection to mycobacterial infection." (PMID 22529866, 2012).
mycoplasma infections (1 paper, 2010). "As lipoproteins from other mycoplasmas can stimulate cells using TLR2, our studies support a role of TLR2, along with TLR1 and/or TLR6, recognition in infection and disease pathogenesis in other mycoplasma infections, including those that affect humans." (PMID 20505832, 2010).
Mycoplasma pneumonia (1 paper, 2020). "In higher vertebrates, TLR1 is known to detect dipalmitoylated and triacylated lipoproteins derived from Mycoplasma pneumonia." (PMID 32466538, 2020).
myelodysplastic syndrome (1 paper, 2025). A clonal hematopoietic disorder characterized by dysplasia and ineffective hematopoiesis in one or more of the hematopoietic cell lines. "Hence, the heightened TLR1/2 signaling implicated in the pathogenesis of myelodysplastic syndrome (MDS) is noteworthy, given its upregulation in patients' dendritic cells and monocytes." (PMID 40922674, 2025).
myocarditis (1 paper, 2024). Myocarditis is a condition that is characterized by inflammation of the heart muscle (myocardium). "However, in patients with myocarditis, TLR1, TLR2, and TLR7 are overexpressed at the mRNA level." (PMID 38715608, 2024).
neurocysticercosis (1 paper, 2011). "However, after induction of neurocysticercosis in adult mice, TLR-1 staining was found almost exclusively in infiltrating cells such as microglia/macrophages." (PMID 21569241, 2011).
neurosyphilis (1 paper, 2023). Infection of the brain or spinal cord by Treponema pallidum. "Laboratory-defined neurosyphilis is associated with a common TLR1 polymorphism, while clinically and laboratory-defined neurosyphilis are both associated with common TLR2 and TLR6 polymorphisms." (PMID 37937275, 2023).
non-Hodgkin lymphoma (1 paper, 2015). Distinct from Hodgkin lymphoma both morphologically and biologically, non-Hodgkin lymphoma (NHL) is characterized by the absence of Reed-Sternberg cells, can occur at any age, and usually presents as a localized or generalized lymphadenopathy associated with fever and weight loss. "Another TLR1 gene SNP, rs4833095, is a well-studied genetic variant, and the TT genotype has been reported to be associated with increased risks of non-Hodgkin lymphoma (NHL) and prostate cancer." (PMID 26226228, 2015).
non-small cell lung carcinoma (1 paper, 2017). A group of at least three distinct histological types of lung cancer, including non-small cell squamous cell carcinoma, adenocarcinoma, and large cell carcinoma. "Higher mRNA expression of TLR1-3 and 5-8 were significantly associated with increased overall survival (OS) when analyzed individually or as a group in both non-small cell lung carcinoma (NSCLC) patients and in the adenocarcinoma (ADC) subtype." (PMID 29190881, 2017).
Obesity (1 paper, 2015). Accumulation of substantial excess body fat. "The magnitudes of the obesity-induced upregulation of the TLR1, TLR4, TLR5, TLR8, TLR9, and TLR12 genes in the visceral adipose tissue were even greater in the diet-induced obesity (DIO) mice than in the ob/ob mice." (PMID 26681840, 2015).
oral squamous cell carcinoma (1 paper, 2024). "The statistically significant differences in the immunostaining of TLR1-10 and NF-κB in healthy control (HC) and oral squamous cell carcinoma (OSCC) samples." (PMID 38593176, 2024).
osteomyelitis (1 paper, 2010). An acute or chronic inflammation of the bone and its structures due to infection with pyogenic bacteria. "In the majority of patients with implant-associated osteomyelitis, however, T cells expressing TLR1, TLR2 or TLR4 were detected." (PMID 21151520, 2010).
osteonecrosis (1 paper, 2022). A none disease characterized by death of bone tissue due to a lack of blood supply. "Furthermore, miRNAs and TFs targeting CD14, CYBB, NOD2, and TLR1 were predicted and a total of 20 differentially expressed miRNAs were identified in patients with osteonecrosis and controls." (PMID 36193326, 2022).
otitis media (1 paper, 2021). Inflammation of the anatomical structures of the middle ear, which is most often caused by an infectious process. "However, it is thought that TLR1 does not likely contribute to recurrence or chronicization of otitis media." (PMID 34360632, 2021).
peripheral nerve injury (1 paper, 2012). Injury to a peripheral nerve. "In a recent study we showed that specifically TLR1 was highly induced after acute peripheral nerve injury and hypothesized that it might play a role in detecting neuronal injury." (PMID 22818207, 2012).
preeclampsia (1 paper, 2021). Preeclampsia is a hypertensive disorder of pregnancy that is characterized by new-onset hypertension with proteinuria presenting after 20 weeks of gestation, and depending on mild or severe forms may initially present with severe headache, visual disturbances, and hyperreflexia. "Pathway analysis of the gene expression data, using multiple predefined pathways, revealed decreased expression of TLR-associated genes in early-onset preeclampsia compared to healthy placentas (P=0.005), mainly due to reduced expression of TLR4 and TLR1." (PMID 34992598, 2021). "The results showed that early-onset preeclampsia placentas displayed reduced expression of complement, and toll-like receptor (TLR) associated genes, specifically TLR1 and TLR4." (PMID 34992598, 2021).
prion disease (1 paper, 2024). A transmissible disease that is caused by a protein that is able to induce abnormal folding of normal cellular proteins, leading to characteristic spongiform brain changes, which are associated with neuronal loss without an inflammatory response. "During the late stages of prion disease, the expressions of TLR1-13 significantly increased." (PMID 38698886, 2024). "Notably, all TLRs (TLR1-13) reached elevated levels at the final stage of prion disease." (PMID 38698886, 2024).
pulmonary sarcoidosis (1 paper, 2024). Sarcoidosis affecting the lung parenchyma. "CTSS, CYBB, FPR2, MNDA, TLR1, and TLR8 could be conducive to improving the diagnostic process and understanding the underlying mechanisms of pulmonary sarcoidosis." (PMID 39364409, 2024). "CTSS, CYBB, FPR2, MNDA, TLR1, and TLR8 could be conducive to improving the diagnostic process and understanding the underlying mechanisms of pulmonary sarcoidosis, and were further verified in PBMC samples using qRT-PCR." (PMID 39364409, 2024).
pulpitis (1 paper, 2017). Inflammation of the dental pulp. "Furthermore, deciduous pulps with pulpitis suffered higher expressions of proinflammatory cytokines (IL-6 and MCP-1) and innate immune response (TLR1, TLR2, TLR3, TLR6, and TLR8) than pulps without pulpitis." (PMID 28377925, 2017).
retinal ischemia (1 paper, 2014). A ischemic disease that involves the retina. "Retinal ischemia was induced, and the changes in the expression of toll-like receptors (Tlr1–Tlr9) were assessed 6 h post-reperfusion by qRT-PCR." (PMID 24754835, 2014).
scrapie (1 paper, 2022). A fatal disease of the nervous system in sheep and goats, characterized by pruritus, debility, and locomotor incoordination. "Remarkably, contrasting expression patterns were found in the hippocampus of the scrapie-infected sheep, in which TLR2 and MyD88 were downregulated (p < 0.01) and TLR1 showed a tendency towards downregulation (p < 0.1)." (PMID 35408945, 2022). "Our study clearly shows that TLRs, and especially TLR4 in sheep and TLR1 and TLR2 in mice, are involved in the pathogenesis of scrapie." (PMID 35408945, 2022). "Our findings in the hippocampus of scrapie-infected sheep reveal an opposite pattern compared with other analyzed brain areas, with the downregulation of TLR1, TLR2, and MyD88 and no cytokine alterations." (PMID 35408945, 2022).
steatosis (1 paper, 2021). Increased lipid within the cytoplasm of cells. "Development of steatosis and even more of early signs of inflammation were markedly attenuated in FFC-fed TLR1−/− when compared to FFC-fed wild-type animals." (PMID 34497333, 2021).
T cell lymphoma (1 paper, 2022). "The expression level of TLR2 was similar in LNs from patients with T cell lymphoma and AOSD; however, TLR1, TLR4, TLR7, and TLR9 expression levels were higher in the LNs of patients with AOSD than in T cell lymphoma." (PMID 35715478, 2022). "The expression levels of TLR1, TLR4, TLR7, and TLR9 increased in the LNs of patients with AOSD compared to that in reactive LN or T cell lymphoma." (PMID 35715478, 2022). "The expression levels of TLR1, TLR4, TLR7, and TLR9 were higher in LNs of patients with AOSD than in LNs of those with T cell lymphoma and reactive lymphadenopathy." (PMID 35715478, 2022). "The expression levels of TLR1, TLR4, TLR7, and TLR9 were higher in LNs of patients with AOSD than in those with T cell lymphoma and reactive lymphadenopathy." (PMID 35715478, 2022). "The comparative analysis shows that the percentage of inflammatory cells expressing TLR1 in LNs from patients with AOSD was significantly greater than that in patients with TB lymphadenitis (p = 0.029), T cell lymphoma (p = 0.004), and reactive LN (p = 0.004)." (PMID 35715478, 2022).